SERPINA3 (serpin family A member 3)
Diseases named in the same sentence as SERPINA3 in open-access papers (continued):
Sharing a sentence is not in itself a finding about the gene and the disease.
lupus nephritis (4 papers, 2019 to 2026). Glomerulonephritis in the context of systemic lupus erythematosus. "Urine SERPINA3 was positively correlated with the activity of lupus nephritis, with SERPINA3 located in endothelial cells and TECs, and predicted renal inflammation and fibrosis, especially early transition of AKI to CKD." (PMID 34276651, 2021). "Under inflammatory conditions such as lupus nephritis and DKD, SerpinA3 translocates to the apical membrane of tubular cells, suggesting a secretion mechanism linked to cellular injury." (PMID 41329353, 2025). "For this purpose, we analyzed serpinA3/Alpha-1-antichymotrypsin levels in patients diagnosed with class III, IV and V lupus nephritis, focal and segmental glomerulosclerosis (FSGS), ANCA associated vasculitis (AAV), and compared them with healthy volunteers." (PMID 31316093, 2019).
multiple sclerosis (4 papers, 2021 to 2025). A progressive autoimmune disorder affecting the central nervous system resulting in demyelination. "Finally, astrocyte cluster 8 (MMP7, SERPINA3, GZMA, and CLIC1) and microglial cluster 2 (DSG2 and TNFRSF25) were elevated in multiple sclerosis patients and suggested the pathogenic role of these biomarkers during multiple sclerosis progression." (PMID 37468977, 2023). "SERPINA3 may signify disease status and progression of multiple sclerosis (MS)." (PMID 40157917, 2025).
renal fibrosis (4 papers, 2019 to 2022). A final common manifestation of a wide variety of chronic kidney diseases characterized by glomerulosclerosis and tubulointerstitial fibrosis. "The expression of ISG20 and SERPINA3 was distinctly increased in renal fibrosis samples compared with normal samples." (PMID 35497880, 2022). "Urinary SerpinA3 levels were equally elevated in both groups despite different degrees of proteinuria and positively correlated with the percentage of renal fibrosis in the biopsy." (PMID 31316093, 2019). "Finally, we observed that the expression of ISG20 and SERPINA3 was distinctly increased in renal fibrosis samples compared with normal samples." (PMID 35497880, 2022). "And Andrea Snchez-Navarro found urinary SerpinA3 could detect renal fibrosis and inflammation, with a particular potential for the early detection of AKI to CKD transition." (PMID 36064366, 2022). "In addition, the role of Serpina3 in the kidney may be to balance inflammation, oxidative stress, and renal fibrosis after kidney injury." (PMID 35308536, 2022). "Thus, our results suggest that serpinA3’s role in the kidney could be to counterbalance the inflammation, oxidative stress and renal fibrosis that follows renal damage." (PMID 31316093, 2019).
acute kidney injury (3 papers, 2019 to 2025). Sudden and sustained deterioration of the kidney function characterized by decreased glomerular filtration rate, increased serum creatinine or oliguria. "In this context, we demonstrated that SerpinA3 serves as an early urinary biomarker for the transition from acute kidney injury (AKI) to chronic kidney disease (CKD) in rats." (PMID 41329353, 2025). "An early elevation and subsequent increase of urinary SerpinA3 (uSerpinA3) were noted in a rat model transitioning from acute kidney injury (AKI) to chronic kidney disease (CKD)." (PMID 39104393, 2024).
amyloid (3 papers, 2023 to 2024). "SERPINA3 is a robust marker of this astrocyte subtype and has been directly implicated in the formation of amyloid plaques." (PMID 39605680, 2024). "We next investigated whether the localized upregulation of SERPINA3 at neuritic plaques could be detected in DLPFC tissue homogenates or the cerebrospinal fluid (CSF) of patients with a high burden of amyloid pathology." (PMID 39605680, 2024). "SERPINA3 and SERPINC1 specifically have also been associated specifically with amyloidotic disorders: both are increased in CSF in early-stage AD, and SERPINA3 has been confirmed to be a major component of senile plaques and to be involved in defibrillation of amyloid in CAA and AD." (PMID 38191511, 2024). "In fact, a CSF proteomic study in the APPPS1 mouse model of amyloidosis highlighted increased levels of proteins related to glial activation and identified APOE and SERPINA3 as CSF biomarkers." (PMID 37303123, 2023).
cervical carcinoma (3 papers, 2013 to 2024). A carcinoma arising from either the exocervical squamous epithelium or the endocervical glandular epithelium. "Colocalization and possible interactions of SERPINA1 and SERPINA3 have been reported in patients with immunological renal disease, in brain tissues of Alzheimer’s patients, or in patient-derived HLA-positive cervical carcinoma." (PMID 38909263, 2024).
Cognitive impairment (3 papers, 2023 to 2025). Abnormal cognition is characterized by deficits in thinking, reasoning, or remembering. "Interestingly, in CSF, a significant negative correlation was found between SERPINA3 and cognitive impairment based on Mini-mental state examination (MMSE) score." (PMID 37369719, 2023).
depression (3 papers, 2019 to 2024). "It has been reported that elevated amounts of the proteins haptoglobin (HP) and alpha-1-antichymotrypsin (SERPINA3) highly correlate with each other and with the severity of depression and negatively correlate with the thyroid-stimulating hormone response to thyrotropin." (PMID 39062058, 2024).
emphysema (3 papers, 2010 to 2022). "High levels of SERPINA3 suggest a continuous accumulation of pro-inflammatory factors in the body, which can exacerbate lung tissue damage and cause emphysema." (PMID 36248880, 2022). "This study comprehensively analyzed the tissue-infiltrating immune cells significantly associated with emphysema phenotype, including M2 macrophages, neutrophils, and resting mast cells, and identified SERPINA3 as a key immune-related gene." (PMID 36248880, 2022). "SERPINA3 was found to be a key immune molecule associated with COPD emphysema through a series of bioinformatics analyses in this study." (PMID 36248880, 2022). "A key gene (SERPINA3) was selected and included in the emphysema risk prediction model." (PMID 36248880, 2022). "Therefore, we speculate that SERPINA3 can be used as a sensitive indicator for early warning of emphysema, and SERPINA3 was also found to be an independent risk factor for emphysema risk in logistic regression analysis." (PMID 36248880, 2022). "In the present study, we found that SERPINA3 was significantly upregulated in emphysema phenotype, and multiple immune cells (such as neutrophils, macrophages, NK cells, mast cells, and T cells) were associated with its up-regulation." (PMID 36248880, 2022). "Mutations in SERPINA3 leading to decreased α-1 anti-chymotrypsin serum levels were associated with the inflammatory lung diseases COPD and emphysema." (PMID 33072128, 2020). "SERPINA3 has also been found to be involved in a variety of physiological functions such as complement cascade, apoptosis, wound healing, and extracellular matrix remodeling, but it has been less studied in emphysema phenotypes." (PMID 36248880, 2022). "The protein expression of SERPINA3 in the emphysema samples was significantly higher than in the non-emphysema samples." (PMID 36248880, 2022).
glaucoma (3 papers, 2021 to 2025). Increased pressure in the eyeball due to obstruction of the outflow of aqueous humor. "Our findings revealed a significant decrease in the mRNA levels of SA1009 and MMP3 in the glaucoma model group compared to the normal group, while SERPINA3, IL1RN, and LCN2 expression increased." (PMID 39125762, 2024). "The three hub genes SERPINA3, IL1R1, and LCN2 were validated as potential diagnostic biomarkers through real-time PCR, showing increased expression in the OGD/R-induced glaucoma model." (PMID 39125762, 2024). "Our study identified and validated six neuroinflammation-related hub genes in glaucoma (SERPINA3, LCN2, MMP3, S100A9, IL1RN, and HP)." (PMID 39125762, 2024). "Moreover, three hub genes, SERPINA3, IL1R1, and LCN2, were validated as potential diagnostic biomarkers for high-risk glaucoma patients, showing increased expression in the OGD/R-induced glaucoma model." (PMID 39125762, 2024).
Insulin resistance (3 papers, 2021 to 2025). Increased resistance towards insulin, that is, diminished effectiveness of insulin in reducing blood glucose levels. "Second, SERPINA3 is strongly associated with insulin resistance and vascular disorders: SERPINA3 influences multiple cellular signalling axes, including crucial components related to insulin signalling pathways and cardiovascular remodelling." (PMID 40076571, 2025).
ischemic stroke (3 papers, 2019 to 2025). A stroke disorder caused by obstruction of blood flow to the brain, due to thrombotic (local blood clot formation) or embolic (due to a blood clot or other material traveling from another site) event. "This dual nature of SERPINA3, potentially acting as both a protective agent in ischemic stroke and a risk factor in ICH, underlines the complexity of cerebrovascular system and the diverse roles that a single protein can play within it." (PMID 37721405, 2024). "On one hand, SERPINA3 may help reduce the damage caused by ischemic stroke by decreasing apoptosis and neuroinflammation in animal models." (PMID 37721405, 2024). "In ischemic stroke, SERPINA3 has been proposed as a potential replacement of glial fibrillary acidic protein (GFAP), a traditional biomarker for activated astrocytes." (PMID 40157917, 2025). "Serine proteinase inhibitor A3 (SERPINA3), a member of the serine protease inhibitor superfamily, has been reported to participate in pathological inflammatory processes of numerous neurological diseases such as ischemic stroke, intracerebral hemorrhage, and Alzheimer's disease." (PMID 37721405, 2024). "However, despite being a potential predisposing factor for ischemic stroke, the relationship between CSVD burden and SERPINA3 has never been investigated in patients with IS." (PMID 37721405, 2024). "For example, some of the differentiation proteins, such as SERPINA3 and CRP involved in inflammatory/acute-phase response, as well as FGA and PLG involved in blood coagulation, were associated with the cardioembolic, large-vessel, and lacunar ischemic stroke subtypes, but not with CBS deficiency." (PMID 31242583, 2019).
liver fibrosis (3 papers, 2012 to 2025). "Our findings pave the way for future therapeutic strategies aimed at inhibiting KCTD17 or restoring SERPINA3 expression to combat liver fibrosis in patients with MASH." (PMID 40744994, 2025). "To explore the molecular mechanisms by which hepatocyte-derived SERPINA3 or Serpina3k mitigates liver fibrosis, we produced CM from AML12 cells transfected with control, mSerpina3k-GFP or hSERPINA3-GFP, which were then applied to HSC-T6 rat HSCs." (PMID 40744994, 2025). "Conversely, forced expression of hepatocyte Serpina3k or SERPINA3 alleviated liver fibrosis by reducing HSC activity through protease-activated receptor 2 (Par2)-mediated TGFβ1 signaling." (PMID 40744994, 2025). "KCTD17 depletion increased SERPINA3 levels and reduced liver fibrosis in mice fed a MASH-inducing diet by inhibiting Par2/TGFβ-mediated activation of hepatic stellate cells." (PMID 40744994, 2025). "Future studies should focus on developing specific KCTD17 inhibitors and advancing the clinical translation of SERPINA3-basaed therapies, which could provide a novel and effective treatment approach for liver fibrosis in patients with MASH." (PMID 40744994, 2025). "In conclusion, this study provides crucial insights into the role of KCTD17 in driving MASH-induced liver fibrosis and elucidates the mechanisms behind the reduced expression of Serpina3k/SERPINA3, as well as the functional consequences in MASH-induced mice and patients with MASH." (PMID 40744994, 2025). "Some studies suggested that SerpinA3 deficiency may be involved in the development and progression of liver fibrosis and cirrhosis Further research is needed to better understand the mechanism of action of Serpina3c/SerpinA3 in chronic liver disease, including NAFLD." (PMID 37288300, 2023). "In line with previous findings, our study observed lower levels of SERPINA3 or Serpina3k in both patients with MASH and mouse models, revealing an inverse relationship between KCTD17 and Serpina3k expression, which contributed to heightened liver fibrosis." (PMID 40744994, 2025).
lymph node metastasis (3 papers, 2011 to 2023). "In addition, we found that INHBA up-regulation and SERPINA3 down-regulation are significantly associated with lymph node metastasis." (PMID 21489260, 2011). "Moreover, we found that INHBA up-regulation was associated with lymph node metastasis (N+) (odds ratio 5.6; 95% confidence interval 1.5 to 21.8; p-value = 0.012), as well as SERPINA3 down-regulation (odds ratio 4.0; 95% confidence interval 1.0 to 15.4; p-value = 0.044)." (PMID 21489260, 2011). "The group with lymph node metastasis at initial diagnosis had low expression of both SERPINA3 and LCN2." (PMID 37408474, 2023).
placental diseases (3 papers, 2013 to 2025). "SERPINA3 is a serine protease inhibitor known to be up-regulated in human placental diseases (including PE) in association with a hypomethylation of the 5' region of the gene." (PMID 23785430, 2013). "In addition to placental diseases, SERPINA3 has been found to be associated with various human diseases, such as Alzheimer’s disease and chronic obstructive pulmonary disease, and multiple forms of cancer, including glioblastoma, colorectal cancer, endometrial cancer, breast cancer, and melanoma." (PMID 41296456, 2025).
Senile plaques (3 papers, 2017 to 2024). Senile plaques are extracellular deposits of amyloid in the gray matter of the brain. "A consistent number of SERPINA3-immunoreactive cortical neurons was found in AD samples where the amyloid of senile plaques and amyloid angiopathy (not shown) was also immunopositive." (PMID 29142239, 2017).
uveitis (3 papers, 2020 to 2025). An inflammatory process affecting a part of or the entire uvea. "Future research should explore the dynamic properties of SERPINA3 in the tear fluid of active and quiescent uveitis eyes." (PMID 34212267, 2021). "In endotoxin-induced uveitis in rats following lipopolysaccharide injection, SERPINA3 mRNA in epithelial cells of the iris and ciliary body was rapidly upregulated as part of the initial inflammatory response." (PMID 32458144, 2020).
viral infection (3 papers, 2024). "One scenario could be that the levels of SerpinA3 molecules are decreased during viral infection in some individuals, leading to inadequate inhibition of CatG." (PMID 39339444, 2024). "SERPINA3, sharing similar GO terms with F2, also underscores its role in the negative regulation of proteolytic processes and acute-phase responses, which are important in controlling inflammation and preventing excessive protease activity that could damage host tissues during viral infections." (PMID 39456924, 2024). "The upregulation of genes, like SERPINA3 and GSTA5, points to a defensive response by the host to mitigate protease activity and oxidative stress, which are likely induced by the viral infection." (PMID 39456924, 2024).
abdominal aortic aneurysm (2 papers, 2018 to 2023). Enlargement and ballooning of the vessel that supplies arterial blood to the abdomen, pelvis and legs. "Additionally, a study revealed that the mRNA expression of SerpinA3 was reduced by 80% in biopsy samples of human abdominal aortic aneurysm (AAA), suggesting that SerpinA3 plays a role in maintaining the structural and functional status of the arterial vessel wall." (PMID 37288300, 2023).
adenoma (2 papers, 2020 to 2022). A neoplasm arising from the epithelium. "Comparing CRC to adenoma samples, some blood particles were still upregulated in CRC patients with CP, HP, and SERPINA3 displaying the largest difference." (PMID 36369736, 2022).
Arthritis (2 papers, 2011 to 2018). Inflammation of a joint. "Furthermore, other authors reported clinical improvement of lupus-like disease and arthritis following administration of a fragment of SERPINA1 and SERPINA3, respectively, which, although belonging to different serpin subgroups, are sharing similar mechanisms of action with OV-SERPINS." (PMID 30254646, 2018).
cardiomyopathy (2 papers, 2022 to 2023). A disease of the heart muscle or myocardium proper. "Consistent with previous studies, our study showed that the number of samples expressing SERPINA3 in the cardiomyopathy group was significantly greater compared to the control group." (PMID 36148059, 2022). "However, in comparison with the control group, the expression level was significantly lower, so this specifies that the dysregulation or imbalance of SERPINA3 gene expression is involved in heart disease progression in those with cardiomyopathy." (PMID 36148059, 2022). "In the training dataset, the cardiomyopathy group's expression levels of CD14, CCL2, and SERPINA3 were significantly lower than the ones in the control group." (PMID 36148059, 2022). "Our findings indicated that SERPINA3 and FCN3 might play a protective role in the pathological process of ischaemic cardiomyopathy by regulating immune cell infiltration." (PMID 36863704, 2023). "The hub genes (CD14, CCL2, and SERPINA3) can be used as markers to distinguish cardiomyopathy from non-cardiomyopathy individuals." (PMID 36148059, 2022). "In conclusion, with the intersection of multiple cardiomyopathy gene sets with different etiologies and WGCNA analysis and LASSO regression analysis, we screened out a key module (turquoise module) and three hub genes involved in cardiomyopathy progression (CD14, CCL2, and SERPINA3)." (PMID 36148059, 2022).
Cerebral ischemia (2 papers, 2023 to 2024). Restriction of arterial blood supply to the brain associated with insufficient oxygenation to support the metabolic requirements of the tissue. "SERPINA3 can attenuate neuronal injury by interfering with granzyme B-mediated neuronal death after cerebral ischemia." (PMID 36959823, 2023).
chronic heart failure (2 papers, 2014 to 2021). "SERPINA3 levels were reported to increase in chronic heart failure patients (HF), though without prognostic value." (PMID 34957248, 2021).
diabetic retinopathy (2 papers, 2021 to 2025). "Elevated serum SERPINA3 in mice increased the transendothelial permeability of retina associated with diabetic retinopathy." (PMID 34276651, 2021).
dilated cardiomyopathy (2 papers, 2024 to 2025). Cardiomyopathy which is characterized by dilation and contractile dysfunction of the left and right ventricles. "In the myocardium of patients with dilated cardiomyopathy however, SERPINA3 expression negatively correlated with the number of naïve B cells." (PMID 40087712, 2025). "Recent studies reported increased circulating levels of SERPINA3 in patients with dilated cardiomyopathy and acute coronary syndromes." (PMID 38909263, 2024).
injury (2 papers, 2023 to 2025). Damage inflicted on the body as the direct or indirect result of an external force, with or without disruption of structural continuity. "SERPINA3 is a secreted peptidase inhibitor from the Serpin family, whose expression is induced by inflammation and nerve injury." (PMID 40157917, 2025). "SerpinA3N shares 70% homology with SerpinA3 in human, Western blotting showed that the expression of SerpinA3 in the hippocampus of patients with TLE and the cortex of patients with traumatic brain injury was higher than that in autopsy patients." (PMID 37422673, 2023).